FGF19 (fibroblast growth factor 19)
Diseases named in the same sentence as FGF19 in open-access papers (continued):
Sharing a sentence is not in itself a finding about the gene and the disease.
diabetes (continued). "This trial indicated that the dysfunction of β-cell or islet is the predominant factor in hyperglycemia that cannot be corrected by weight loss, which is consistent with our study that the relationship between FGF19 and diabetes was to a small degree moderated by BMI reduction." (PMID 41522208, 2026). "A combined CV risk model incorporating biomarker clusters, relevant SNPs, and traditional risk factors achieved good discriminative ability (C-index = 0.80), with the FGF19/β-Klotho cluster showing predictive importance comparable to diabetes and previous CV history." (PMID 41682686, 2026). "Results could be useful to delineate the specific roles of bile acids and FGF-19 in glucose metabolism and their potential as targets for diabetes treatment and prevention." (PMID 41169463, 2025). "Descriptives of the levels of bile acids groups and FGF-19, overall and by diabetes status." (PMID 41169463, 2025). "Several studies have shown that FGFs, particularly FGF-2, FGF-19, and FGF-23, are altered in diabetes and may be associated with complications such as nephropathy and impaired wound healing." (PMID 40943671, 2025). "Previous research has shown that FGF19 administered to cerebral ventricles results in decreased food intake, lower glucose levels and improved insulin sensitivity in mice fed a high fat diet indicating a potential link between diabetes and FGF19." (PMID 35116006, 2021). "Transgenic mice over-expressing the FGF19 protein are resistant to diet-induced diabetes." (PMID 33101202, 2020). "To analyse whether serum FGF19 is independently correlated with insulin resistance, secretion, sensitivity and diabetes therapy, we performed multiple stepwise regression analysis." (PMID 31572498, 2019). "The ileal-derived hormone, fibroblast growth factor 19 (FGF-19), may promote weight loss and facilitate type-2 diabetes mellitus remission in bariatric surgical patients." (PMID 28202005, 2017). "It is of particular interest that it was either lower FGF19 or higher FGF21 serum levels that were signifciantly associated with diabetes or cardiometabolic phenotypes but never the two together." (PMID 25664662, 2015). "In addition FGF19 reversed dietary diabetes and improved glycogen synthesis in an insulin-independent pathway." (PMID 24465600, 2014). "Future work should consider broader inflammatory panels and tissue-specific markers to evaluate whether FGF19 relates to diabetes risk through inflammatory signaling independent of adiposity." (PMID 41522208, 2026). "First, because this study used a cross-sectional design, temporality cannot be established and causal inference is limited; reverse causation is also possible (e.g., dysglycemia, insulin resistance, or diabetes treatment may influence circulating FGF19 concentrations)." (PMID 41522208, 2026). "Since FGF-19 and cBAs showed negative and positive, respectively, independent associations with insulin resistance, these two factors should be considered together in future studies, to better understand the mechanisms that contribute to diabetes risk." (PMID 41169463, 2025). "Therefore, the beneficial impact of FGF19 on glucose, lipid and bile acid homeostasis raise the possibility to pursue FGF19 as a therapeutic target for treating various metabolic disorders including diabetes, non-alcoholic fatty liver disease and cholestatic liver diseases." (PMID 35264190, 2022). "FXR stimulates the secretion of fibroblast growth factor 19 into the portal circulation and activates its fibroblast growth factor 4 liver receptor, leading to decreased gluconeogenesis glycemia and improved insulin sensitivity and glucose and lipid metabolism in diabetes." (PMID 35907885, 2022).
diabetes (continued). "Taken together, these data provide evidence that FGF21 and the FGF19-BA pathway are significantly perturbed in severe diabetes and could represent suitable targets for the development of a new class of treatments for diabetes provided that the pro-oncogenic effects of FGF19 could be curtailed." (PMID 25664662, 2015). "Moreover, FGF19 and bile acids were found to increase predominantly in patients that experience diabetes remission after Roux-en-Y gastric bypass surgery, compared to patients without diabetes or patients with diabetes that do not experience remission after RYGB surgery." (PMID 24465600, 2014). "This could potentially be beneficial in reducing risk for diabetes development because higher FGF19 levels are associated with non-diabetes and diabetes remission after RYGB surgery." (PMID 24465600, 2014). "While systemic treatment with FGF19 reduced weight gain and reversed diabetes in obese mice, hepatic responses to FGF19 have been shown to be impaired in obese mice and patients with steatosis, suggesting that FGF19 may also act independently from the liver in these contexts." (PMID 24567901, 2014). "This study aimed to investigate the relationship between serum fibroblast growth factor-19 (FGF19) levels and diabetes, as well as the potential mediating role of body mass index (BMI)." (PMID 41522208, 2026). "In addition, reduced fasting serum FGF19 levels have been observed in patients with inflammatory bowel disease, indicating a potential link between FGF19 and oxidative stress, inflammation, and immune response, all of which contribute to the pathogenesis of diabetes." (PMID 41522208, 2026). "Fibroblast growth factor 19 (FGF-19) hormone levels were negatively correlated with CAD (defined by coronary angiography), independently of BMI, hypertension, dyslipidemia, and diabetes." (PMID 36013368, 2022). "FGF19 was found to decrease in subjects with isolated-impaired fasting glucose (I-IFG) and type 2 diabetes mellitus (T2DM)." (PMID 28729691, 2017). "Intravenous (iv) administration of FGF19, also prevented genetic (ob/ob) and diet-induced (HFD) obese mice to develop diabetes by improving glucose metabolism." (PMID 29163019, 2017). "The FGF family has shown a great potential in the treatment of diabetes, particularly FGF-1, FGF-19 and FGF-2120." (PMID 27808173, 2016). "FGF19 and FGF21 are enterohepatic hormones that play important roles in the pathophysiology of diabetes." (PMID 25664662, 2015). "FGF19 and bile acids increase after RYGB surgery particularly in patients that experience diabetes remission." (PMID 25664662, 2015). "Our study discovers a monotonic and negative relationship between serum FGF19 levels and diabetes in the Chinese population, and this relationship is partially mediated by the reduction of BMI." (PMID 41522208, 2026). "Endocrine FGFs (FGF-19, FGF-21) may also regulate glucose and lipid metabolism, acting as potential biomarkers in diabetes." (PMID 40943671, 2025). "Given the clinical relevance of glycemic control, Spearman’s rank correlation analysis was conducted to assess the relationship between glycated hemoglobin (HbA1c) levels and concentrations of selected fibroblast growth factors (FGF-2, FGF-19, FGF-22, and FGF-23) in patients with diabetes (n = 73)." (PMID 40943671, 2025). "In light of these limitations, further large-scale studies with more homogeneous cohorts, incorporating medication tracking, and longitudinal follow-up are necessary to validate the current results and clarify the mechanistic and prognostic roles of FGF-2, FGF-19, FGF-22, and FGF-23 in diabetes." (PMID 40943671, 2025). "In this study, FGF-19 concentrations were significantly lower in both type 1 and type 2 diabetes compared to the control group, consistent with previous reports linking reduced FGF-19 levels to diabetes." (PMID 40943671, 2025). "FGF-2, FGF-19, FGF-22, and FGF-23 likely significantly impact diabetes and its complications." (PMID 40943671, 2025).
diabetes (continued). "Because of their effects on liver and adipose tissue, especially FGF19 and FGF21 may be interesting with regard to the treatment of diabetes mellitus." (PMID 36699319, 2022). "Pre-operatively, those with diabetes had lower FGF19 and bile acid levels than nondiabetic patients." (PMID 35116006, 2021). "LCA is an agonist of farnesoid X receptor (FXR), activation of which reduces BA synthesis in the liver via fibroblast growth factor-19 signaling, whereas GUDCA is an antagonist for FXR, recently shown to improve metabolic endpoints in humans related to diabetes." (PMID 31840162, 2020). "Before the surgery, lower concentrations of FGF19 and fatty acids were observed in people with diabetes compared to nondiabetic patients regardless of BMI." (PMID 30927227, 2019). "This is consistent with the results obtained in people with diabetes and metabolic syndrome in whom FGF19 concentration negatively correlated with BMI, triglycerides, HDL cholesterol, CRP, and glycated hemoglobin levels." (PMID 30927227, 2019). "When serum levels of FGF19 were < 200 mg/mL and FGF21 > 500 mg/mL, 91% of patients had diabetes." (PMID 25664662, 2015). "Prospective clinical trials using pharmacologic and/or nutritional interventions that can modulate circulating FGF19 and FGF21 levels could help elucidate further the exact roles of these two hormones in the pathophysiology of diabetes." (PMID 25664662, 2015). "When combining high FGF21 with low FGF19 levels, 91% of Class III obese patients had diabetes." (PMID 25664662, 2015). "Moreover, FGF19 serum levels increase following RYGB surgery and particularly more so in patients that experience remission of diabetes." (PMID 25664662, 2015). "However, our study confirmed the negative relationship between FGF19 and diabetes with a much larger sample size, which enhanced the statistical power and generalizability." (PMID 41522208, 2026). "We did not observe a significant inverse association between FGF19 and FBG, possibly due to the lower diabetes prevalence in our cohort (~ 8% vs. ~ 28%) and differences in exposure modeling (continuous FBG in our study vs. categorized glycemic groups in the prior study)." (PMID 41522208, 2026). "In the present study, we tested the hypothesis that circulating levels of FGF19 and FGF21 correlate with each other, and that along with genes regulating hepatic pathways of bile acid synthesis are dysregulated in diabetes and in particular in patients that fail to remit diabetes after RYGB surgery." (PMID 25664662, 2015). "In addition, using liver wedge biopsies taken during surgery, we compared the expression levels of FGF21 and of key genes in the FGF19-BA pathway between diabetic and non-diabetic patients and also between diabetic patients that remit or do not remit diabetes after RYGB surgery." (PMID 25664662, 2015). "In T1D, FGF19 and VEGF and sklotho was not correlated with the duration of diabetes." (PMID 36927328, 2023). "Negative correlation between the levels of FGF19 and VEGF, and positive correlation between the levels of FGF19 and Soluble Klotho may suggest its possible involvement in the development of chronic complications of diabetes." (PMID 36927328, 2023).
Insulin resistance (42 papers, 2011 to 2026). Increased resistance towards insulin, that is, diminished effectiveness of insulin in reducing blood glucose levels. "To investigate the mechanism underlying acupuncture-mediated improvement of insulin resistance, we employed qPCR to measure the expression levels of fibroblast growth factor 19 (FGF19), a gene associated with the FXR signaling pathway." (PMID 41514462, 2026). "The study reveals that serum Orexin A, PBP4, and FGF19 are significantly associated with insulin resistance and neonatal weight in GDM, with BMI modulating the impact of PBP4 on insulin resistance." (PMID 40859577, 2025). "Orexin A, PBP4 and FGF19 are negatively associated with both insulin resistance (P < .01, P < .01, P = .03) and birth weight (P = .02, P < .01, P = .02)." (PMID 40859577, 2025). "In this elderly Italian population, primary and secondary cBAs were positively associated with insulin resistance, after adjusting for each other, whereas FGF-19 negatively." (PMID 41169463, 2025). "FGF-19 deficiency can lead to abnormalities in bile acid metabolism, which negatively affects the regulation of glucose–lipid metabolism, exacerbating the insulin resistance characteristic of GDM." (PMID 40648894, 2025). "This disruption leads to deficient secretion of FGF19, which contributes to insulin resistance and hyperglycemia in mice and humans." (PMID 39596418, 2024). "GM dysbiosis caused by misaligned meal timing can also affect the fluctuation of primary and secondary bile acids (BAs), leading to deficient secretion of FGF19 and subsequent insulin resistance and hyperglycemia in mice and humans." (PMID 39596418, 2024). "FGF-19 has been increasingly studied for its role in metabolic regulation, particularly in the context of insulin resistance (IR), and appears to influence insulin sensitivity." (PMID 41169463, 2025). "This study aims to explore the correlation between serum levels of Orexin A, PBP4, and FGF19 with insulin resistance and neonatal weight in women with GDM, providing a comprehensive analysis of these relationships." (PMID 40859577, 2025). "For every one-unit increase in FGF19 levels, insulin resistance (HOMA-IR) is estimated to decrease by 0.20 units (95% CI: −0.35 to −0.05, P = .03)." (PMID 40859577, 2025). "Consistent with this, reduced circulating FGF19 levels have been demonstrated in CMD patients, and systemic FGF19 levels inversely correlate with the atherogenic index and other cardiometabolic traits such as insulin resistance." (PMID 41303064, 2025). "The purpose of this study was to investigate the relationships between serum biomarkers Orexin A, PBP4, FGF19, and insulin resistance as measured by HOMA-IR, and neonatal weight in patients with gestational diabetes mellitus (GDM)." (PMID 40859577, 2025). "In conclusion, our study provides evidence for the involvement of Orexin A, PBP4, and FGF19 in the pathophysiology of insulin resistance and neonatal weight in GDM." (PMID 40859577, 2025). "Reduced circulating FGF19, altered conjugation patterns and expanded bile acid pool size have been linked to insulin resistance and type 2 diabetes in recent cohorts, supporting translational relevance of the FXR-FGF19 feedback loop identified in rodents." (PMID 41465592, 2025). "FGF19 and FGF21 are thought to be associated with insulin resistance, an essential element in the pathogenesis of GDM." (PMID 38139126, 2023). "FGF19 and FGF21 have been shown to be associated with insulin resistance, which suggests their potential relevance as predictive factors for GDM development." (PMID 38139126, 2023). "The importance of insulin resistance in BA metabolism has been demonstrated in different studies that showed the concomitant increase of insulin levels and a decrease of FGF19 levels in line with the development of fibrosis." (PMID 36531484, 2022).
Insulin resistance (continued). "The biological evidence supports the fact that FGF 19 tends to have a closer interaction with DM and insulin resistance, while FGF 21 plays a greater role in the spectrum of fatty liver disease." (PMID 35277004, 2022). "Fibroblast growth factor-19 (FGF19) is a hormone-like enterokine which can reduce the blood glucose of insulin resistance model mice (ob/ob mice and high-fat diet mice) and enhance insulin sensitivity." (PMID 34307371, 2021). "We analyzed the role of FGF19, FGF21 and Klotho protein in children with normal body weight as well as in overweight and obese subjects and explored their associations with insulin resistance (IR) and metabolic syndrome (MS) and its components." (PMID 32546231, 2020). "Patients with NAFLD and insulin resistance had an impaired hepatic response to FGF19, leading to the dysregulation of lipid homeostasis." (PMID 31181641, 2019). "In rodent model studies, FGF19 is able to decrease weight and improve metabolic disorders and insulin resistance." (PMID 31572498, 2019). "Our group and others have shown that serum levels of FGF-19 rise significantly 4h after oral lipid ingestion and this response is blunted in patients with non-alcoholic fatty liver disease and insulin resistance." (PMID 26863103, 2016). "Then, in two mouse models of insulin resistance, leptin-deficiency and high-fat diet feeding, third intra-cerebro-ventricular infusions of FGF19 improved glycemic status, reduced insulin resistance and potentiated insulin signaling in the periphery." (PMID 24567901, 2014). "Remarkably, FGF19 treatment has hypoglycemic actions that remain potent in models of genetic and acquired insulin resistance." (PMID 24567901, 2014). "Overexpression or injection of FGF19 into mice has been shown to affect metabolic rate and improves insulin resistance and dyslipidemia." (PMID 22662222, 2012). "The activity of FGF19 to improve insulin resistance and hyperglycemia in obese and diabetic mice is shared by a related endocrine FGF, FGF21." (PMID 21437243, 2011). "The intracerebroventricular (ICV) effects of FGF19 in models of metabolic dysfunction have been studied in obese mice and rats, and it was observed that FGF19 acts on the hypothalamus, reducing food intake and body weight gain, and improving glucose tolerance and insulin resistance." (PMID 39590343, 2024). "Levels of FGF-19, a classical surrogate of intestinal BA action, are lower despite higher serum bile acid levels in insulin resistance, although the effect of improved insulin resistance on these parameters appears to depend on the treatment modality." (PMID 36100090, 2022). "This implies that FGF 19 may also provide predictive value regarding improvements in insulin resistance and remission of T2DM." (PMID 35277004, 2022). "We hypothesize that lifestyle interventions introduced to women with early-diagnosed GDM to avoid weight gain and increased insulin resistance could have prevented significant reductions in FGF-19 levels in the second and third trimesters." (PMID 35566542, 2022). "In addition, in patients with insulin resistance, the synthesis of intestinal FGF19 is reduced and correlates inversely with progression to liver fibrosis." (PMID 36531484, 2022). "Practically, FGF 19 signaling cascade reduces liver steatosis and insulin resistance." (PMID 35888771, 2022). "Moreover, the glucose uptake test with 2‐NBDG also showed that FGF19 promoted glucose uptake and alleviated PA‐induced insulin resistance to some extent." (PMID 33751819, 2021). "Recently reported observations have suggested the CNS to play a role in FGF19-mediated glucose homeostasis regulation, based on demonstrations of intra-cerebroventricular infusions of FGF19 improving glycemic status and potentiating peripheral insulin signaling in a murine insulin resistance model." (PMID 30297626, 2018).